EGF (epidermal growth factor)
Diseases named in the same sentence as EGF in open-access papers (continued):
Sharing a sentence is not in itself a finding about the gene and the disease.
cancer (continued). "In endothelial cells, ROS-mediated angiogenesis via various stimuli via angiopoietin-I, angiogenin, VEGF, EGF, urotensin-II, shear stress, and hypoxia is a major contribution to cancer." (PMID 35421091, 2022). "Previous work revealed PKM2 is translocated to the nucleus in human cancer cells in response to EGF, a process resulting from PKM2 successively binding to PIN1 (peptidylprolyl cis/trans isomerase, NIMA-interacting 1) and importin α5." (PMID 36476366, 2022). "The suppression of AQP3 expression reduces EGF-induced H2O2 influx and attenuates EGF signaling cascades in various cancer cells." (PMID 35847914, 2022). "Another ubiquitin ligase, RNF144A, was reported to exert a positive effect on cell proliferation in EGF-dependent human cancer and immortalized embryonic cell line models, by maintaining EGFR expression." (PMID 35634494, 2022). "A previous study has demonstrated that ATXN2L upregulated by epidermal growth factor promotes cancer cell invasiveness and oxaliplatin resistance." (PMID 35061901, 2022). "Various growth factors, such as epidermal growth factor (EGF) and fibroblast growth factors (FG), are released during the process of inflammation, which increases cell proliferation and, hence, causes cancer." (PMID 36558921, 2022). "Aberrant activation of EGF/EGFR signaling contributes to cancer proliferation, epithelial-mesenchymal transition, and metastasis." (PMID 35502895, 2022). "The Cr(VI)‐induced ALDH1A1 maintains self‐renewal of the CrT/TIC subpopulation and promotes expression and secretion of EGF from CrT/TICs to activate EGFR signalling of differentiated cancer cells, promoting LUSC tumourigenesis." (PMID 36504325, 2022). "High epidermal growth factor (EGF) expression in TAMs activates epidermal growth factor receptors (EGFRs) in the cancer cells which in turn promotes metastasis and CSF‐1 secretion." (PMID 34914196, 2022). "Using these two controls in our study, we were able to screen PD153035, cetuximab, and caffeine for their role in EGF inhibition in cancer treatment." (PMID 35203275, 2022). "Previous studies have shown that PKCζ plays an important role in EGF-induced chemotaxis of cancer cells." (PMID 36330442, 2022). "AMPK regulates oncogenic signaling downstream of EGFR overexpression and EGF stimulation in other cancer contexts, suggesting AMPK as a potential link between EGFR and GABP regulation." (PMID 36130485, 2022). "In the study, the EGFR expression in carcinoma cells was prolonged for 10 h when 10 nM of EGF was exerted, as compared to only 4 h of EGFR expression in 0.4 nM EGF." (PMID 36286420, 2022). "The most obvious candidate was FGF/ERK, as it is key for exit from naive pluripotency, and its EGF/ERK counterpart been shown to be regulated by endocytosis in cancer cells." (PMID 33217323, 2021). "EGFR activation is partly due to α2,6 sialylation of the EGFR by ST6Gal1, which affects EGF-induced cancer cell proliferation." (PMID 33827580, 2021). "As a secreted serine protease, KLK8 is known to mediate the proteolytic process of pro-EGF into mature EGF.EGF is known to activate PI3K/Akt/mTOR pathway in a variety of cancers." (PMID 34395235, 2021). "A similar study examined the crosstalk between EGF and steroid hormones, which recurs in embryogenesis and is co-opted in cancer." (PMID 34206026, 2021). "EGF/EGFR signaling is hyperactive in a broad array of human cancers including malignant breast cancer, skin tumor, non-small cell lung cancer (NSCLC), colorectal cancer, and pancreatic cancer." (PMID 34433808, 2021). "A variety of targeted therapies that block the EGF/EGFR pathway have proven to be an effective therapy for cancer." (PMID 34804932, 2021). "In this sense, EGF signalling pathway, a key pathway in cancer, has been connected with sorafenib in terms of resistance." (PMID 34655447, 2021).
cancer (continued). "Upon stimulation with UV irradiation, the chemical structure of ZnO was rearranged to release docetaxel and EGF, resulting in obstruction of the growth of cancer cells." (PMID 33644041, 2021). "Accordingly, breast cancer cells expressing EGFR secrete CSF-1 and attract macrophages, which secrete EGF in the vicinity of cancer cells, thus permitting cancer cell migration." (PMID 34206026, 2021). "Given the importance of EGF-conjugates in cancer treatment, it is crucial to improve the capability of EGF-conjugates to inhibit cancer cell growth and increase anti-cancer effect with its low dosage." (PMID 34512175, 2021). "The therapeutic cancer vaccine recombinant Epidermal Growth Factor (EGF)-CRM197 is a novel combined conjugate EGF with CRM197 as a carrier protein." (PMID 34804932, 2021). "The proliferation of many types of cancer cells is partly controlled by the autocrine EGF stimulation loop because epidermal growth factor receptor (EGFR) is consistently overexpressed in these cells." (PMID 34368119, 2021). "For example, it has been reported that EGF promotes the migration of MDA-MB-231 cells.To investigate if ABRACL is involved in elicited migratory responses of cancer cells, we employed the EGF-stimulated MDA-MB-231 cell migration assay." (PMID 33670794, 2021). "This provided at least one possible mechanism of FOXP2 down-regulation in EGF-induced EMT progression in the cancer cells." (PMID 33718155, 2021). "EGF is a key factor involved in cell growth and differentiation of normal and cancer tissues and, among other factors, in tissue repair processes." (PMID 34445479, 2021). "Taken together, our results illustrate a novel regulatory role of EGF-ERK-SOX9-TSPAN8 signaling in cancer cell migration and invasion." (PMID 34163029, 2021). "Epidermal growth factor (EGF)-nanoparticle conjugates have the potential for cancer therapeutics due to the unique cytotoxic activity in cancer cells with EGF receptor (EGFR) overexpression." (PMID 34512175, 2021). "The recombinant EGF-CRM197 cancer therapeutic vaccine is safe, well tolerated, and can effectively induce the production of high levels of anti-EGF antibodies that neutralize EGF in patients with advanced solid tumors." (PMID 34804932, 2021). "The epidermal growth factor (EGF) pathway plays critical roles during cancer cell epithelial-mesenchymal transition (EMT) process and metastasis." (PMID 33937024, 2021). "We found that GnRH agonist triptorelin dose-dependently reduced basal and epidermal growth factor (EGF) induced proliferation of HEC-1A EC cancer cell line under serum-free and phenol red-free conditions." (PMID 33535622, 2021). "Previously, we showed that cancer stem-like cell populations were enriched by maintaining cells with serum-free culture media supplemented with epidermal growth factor (EGF) and basic fibroblast growth factor (bFGF)." (PMID 34575486, 2021). "Macrophages enhance cell migration via expression of epidermal growth factor (EGF) which binds the EGF receptor found specifically on the cancer cells." (PMID 33235291, 2021). "Recently, it has been identified that the conjugation of epidermal growth factor (EGF) to gold nanoparticles (GNPs) can gain an enhanced apoptotic efficiency in cancer cells." (PMID 34512175, 2021). "SPHK2 has basal activity towards sphingosine; however, SPHK2 can be activated by a variety of factors and conditions, including epidermal growth factor (EGF) in cancer cells Pyne and Pyne (2020) and hypoxia in cerebral microvascular endothelial cells." (PMID 34055895, 2021). "Human SPHK2 is phosphorylated at Ser351 and Thr578 by extracellular signal-regulated kinase 1 (ERK1), and phosphorylation of these residues is important for EGF-mediated migration of cancer cells." (PMID 34055895, 2021). "They demonstrated that the junctional motion dynamics of squamous-columnar cells with increasing epidermal growth factor (EGF) became similar to those of squamous-cancer cells." (PMID 33971636, 2021).
cancer (continued). "TAMs secrete cell growth factors such as TNF-α, TGF-β, epidermal growth factor (EGF), and platelet-derived growth factor, which induce cancer tissue growth." (PMID 35008577, 2021). "Herein, we demonstrate successful enhancement of the anti-cancer activity of EGF-gold nanoparticle conjugates (EGF-GNPs) by controlling the EGF orientation on the surface of the nanoparticle through site-specific mutagenesis." (PMID 34512175, 2021). "In particular, Cur and Res can inhibit cancer growth through the inhibition of pathways related to epidermal growth factor (EGF) and vascular endothelial growth factor (VEGF), pro-inflammatory cytokines, and pro-inflammatory enzymes." (PMID 34361819, 2021). "Squamous cell histology dominates the cellular lineage in H&N cancers, and epidermal growth factor (EGFR) is almost always expressed in squamous cell carcinoma of the H&N (SCCHN)." (PMID 34123780, 2021). "On the one hand, anti-cancer compounds containing a BPA conjugate with an epidermal growth factor (EGF) ligand or anti-EGFR antibody (mAbs, cetuximab (C225)) or anti-EGFRvIII mutation antibody (L8A4), and specifically recognize wild-type EGFR and EGFRvIII." (PMID 34094980, 2021). "In this study the authors have shown that highly sulfated (1→3)-α-L-fucan from S. cichorioides demonstrates the most pronounced cancer-preventive activity in the model of EGF-induced malignant transformation of JB6 P+ Cl41 cells." (PMID 34677457, 2021). "MMP3-mediated cleavage of other growth factors such as heparin-bound epidermal growth factor and transforming growth factor β promotes cancer cell proliferation and epithelial-mesenchymal transition (EMT)." (PMID 34072157, 2021). "On the other hand, it has been previously reported that EGF stimulation in cancer cells can promote both the homodimerization of EGFR and heterodimerization of EGFR with human epidermal growth factor receptor 2 (HER2)/Erb-B2 receptor tyrosine kinase 2 (ErbB2)." (PMID 33705793, 2021). "Nuclear localization of SHC binding and spindle-associated 1 (SHCBP1) induced by EGF enhances the CBP/β-catenin interaction and activates β-catenin signaling and cancer proliferation." (PMID 34359854, 2021). "Crystal structure analysis have revealed that these antibodies bind to domain III of EGFR and thereby inhibit binding of EGF, which in turn blocks the signaling and proliferation of cancer cells." (PMID 33707468, 2021). "Monensin is a Na+ ionophore and has been shown to slow down EGF-induced EGFR degradation in cancer cells." (PMID 34025398, 2021). "RAS-activating mutations and epidermal growth factor (EGF) hyper-signaling, which potentiates cell proliferation, are common in cancer." (PMID 34946644, 2021). "Relocalization of PDC‐E1 has been observed in cancer cells that were serum‐starved or stimulated with epidermal growth factor or a mitochondrial respiration inhibitor (rotenone)." (PMID 34418283, 2021). "It has been known for some time that the addition of epidermal growth factor (EGF) promotes the restoration of the corneal epithelium and patients using EGFR inhibitors as anti-cancer therapies are at increased risk of corneal erosions." (PMID 34572058, 2021). "It is well-known that EGF is involved in cancer progression by promoting cell proliferation and invasion." (PMID 34069970, 2021). "Using point mutants of Rlip, we have shown that the rate of internalization of EGF in cultured cancer cells is decreased in proportion to the transport activity of Rlip." (PMID 34944997, 2021). "Signaling through all major pathways that promote cancer growth downstream of EGF is also impaired similarly, contributing to the anticancer effects of Rlip inhibition." (PMID 34944997, 2021). "In another study, DNA origami structures decorated with both integrin specific peptides and epidermal growth factor (EGF) ligands were utilized in the investigation of cancer cell adhesion." (PMID 34443832, 2021).
cancer (continued). "Altogether, these results confirm that EGFR degradation due to erlotinib and EGF treatment in our 3D cancer cell culture system occurs via lysosomes." (PMID 34572731, 2021). "Cadherin EGF LAG seven‐pass G‐type receptors (CELSRs) are involved in the progression of various types of cancer." (PMID 33811453, 2021). "Cetuximab selectively binds to EGFR and competitively inhibits the binding of EGF and other ligands, preventing its activation, eventually inhibiting the growth of cancer cells and production of MMP and EGF and inducing apoptosis." (PMID 33946823, 2021). "It appeared that the protein, called GMI (Ganoderma microsporum immunomodulatory), inhibited epidermal growth factor-mediated invasion of cancer cells." (PMID 34439756, 2021). "Among the most widely investigated, receptor tyrosine kinase (RTK) is the epidermal growth factor (EGF) family which is also called erythroblastic B (ErbB) receptors due to its various developmental, physiological functions in human and for triggering cancer." (PMID 33504239, 2021). "IGF-1 and EGF are known to be overexpressed in most types of cancer tissues and contribute to cancer resistance to existing treatments." (PMID 35008759, 2021). "For example, patients with corneal abrasions and epithelial lesions saw marked healing with EGF treatment, as did corneal erosions associated with the use of cetuximab (an EGFR inhibitor) to treat cancer and traumatic corneal ulcers." (PMID 34572058, 2021). "Epidermal growth factor was discovered in 1962, and the first clues on the role of EGF/EGFR in cancer cell biology appeared in the 1980s." (PMID 34211836, 2021). "GM-CSF and EGF secreted from cancer cells have also been reported to induce M2 polarization of TAMs." (PMID 34885065, 2021). "Studies have shown that serum EGF levels are correlated with tumorigenesis and prognosis of cancer patients." (PMID 34804932, 2021). "This increases the secretion of two enhancers of cancer cell migration: EGF and stromal cell-derived factor 1 (SDF-1/CXCL12)." (PMID 34207247, 2021). "To compare the impact of two important growth factors on cancer cell migration, we treated A549 cells that were kept in serum-free growth medium with either TGFβ, EGF, or a combination of both." (PMID 33777943, 2021). "Phosphorylation is considered a key modification of BECN1, and several reports have demonstrated that EGF/EGFR signaling negatively regulates autophagy by directly binding to BECN1 in cancer cells." (PMID 34131122, 2021). "Consistently, phosphorylation of this residue has been also observed in Epidermal Growth Factor (EGF)-stimulated HeLa cells, as well as in the kinome analysis during cell cycle, and in human cancer cells phospho-proteome." (PMID 32471307, 2020). "Through real time PCR, we found that EGF promoted the mRNA expression of PD-L1 in these cancer cells." (PMID 33324209, 2020). "Caco-2 cancer cells were treated with 100 ng/mL EGF for 24 hours, and the changes in the expression level of miR-217 were assessed using real-time PCR." (PMID 32148496, 2020). "Specifically, cancer cells that were exposed to CMtx-EGF were re-sensitized to cetuximab at a level resembling baseline response." (PMID 32481658, 2020). "CD44 and Nanog belong to several regulators of CSCs and are abnormally high in CSC and can be used as markers for CSC and it is known that their expression is increased by EGF signaling pathway in several cancers including HCC16,17." (PMID 32376896, 2020). "A SH-SAW biosensor was studied experimentally and numerically to investigate its frequency shift with two types of sensing films, APTES and glutaraldehyde, for detecting cancer-related biomarker antigen EGF, especially at a trace level." (PMID 32764513, 2020). "In order to translate our findings to a more physiologically relevant cancer model, we repeated our cetuximab and EGF experiments in KRAS wild-type patient-derived CRC organoids, ORG12620." (PMID 32481658, 2020).
cancer (continued). "When the EGF autocrine loop is partially repressed, increases in the stellate cell population lead to increases in the proliferation of cancer cells." (PMID 32696951, 2020). "Our results suggest that EGF-TiO2 PEG NPs can be effectively used in cancer bioimaging methods such as PDD and for cancer therapies such as PDT with a decreased risk of cancer overgrowth." (PMID 33003324, 2020). "In this study, RPE not only inhibited cyclin D1 and c-myc expression under basal conditions for A549 cells, but also suppressed cancer growth under artificial EGF-treated conditions." (PMID 33158043, 2020). "To verify that EGF was the specific CMtx-factor that conferred resistance to cetuximab, we incubated CMtx with an EGF-neutralizing antibody (CMtx-EGF), which led to cancer cell response to cetuximab through reduced cell viability." (PMID 32481658, 2020). "The epidermal growth factor (EGF) released by TAMs increases the expression of ICAM-1 in cancer cells and upregulates the αMβ2 integrin in macrophages, facilitating both cells’ interactions." (PMID 32456078, 2020). "In cancer cells, EGF stimulation increased levels of pERK1/2, whereas cetuximab treatment shut down this pathway, as evidenced by undetectable pERK1/2 levels." (PMID 32481658, 2020). "Given that IL-8 is a crucial player in cancer development, we examined the effects of R406 on EGF-induced IL-8 expression in A431 cells." (PMID 32093123, 2020). "To date, two monoclonal antibodies, cetuximab and panitumumab, capable of inhibiting EGF or growth factor-mediated signaling pathways have been used for cancer therapy." (PMID 32204508, 2020). "Given that TAMs secrete various growth promoting factors, such as EGF, FGF, et cetera, in the TME, which causes proliferation of cancer cells." (PMID 32992449, 2020). "After 24 h EGF treatment, the pathways Transcriptional misregulation in cancer, Jak-STAT signaling pathway, PI3K-Akt signaling pathway and Proteoglycans in cancer were enriched." (PMID 33115415, 2020). "In our previous studies, however, we demonstrated that the absence of the Gαi2 protein impaired the migratory capability of several cancer types, when EGF was used as chemotactic inducer, revealing a novel mechanism that need to be evaluated." (PMID 32575572, 2020). "This prognostic signature successfully verified the chemopreventive effect of erlotinib, a small molecule EGF pathway inhibitor, in multiple rodent models, and also led to the initiation of a cancer chemoprevention clinical trial (NCT02273362)." (PMID 33255794, 2020). "Recently, a novel strategy to treat cancer cells expressing a higher level of the EGFR used an epidermal growth factor-gold nanoparticle (EGF-GNP) conjugate complex." (PMID 31963462, 2020). "Conversely, low EGF levels have been found in cancer subjects with recurrence, and an inverse correlation between its concentrations and survival has been documented in these subjects." (PMID 31991775, 2020). "When EGF is used as a ligand in drug delivery vehicles, it can affect cellular signaling and stimulates events leading to enhances cancer cell proliferation." (PMID 32194412, 2020). "Previous studies have been shown that many natural compounds such as quercetin, resveratrol, and delphinidin inhibit motility and invasiveness via EGF-stimulated EMT suppression in several types of cancer cells, including HCC49–51." (PMID 32376896, 2020). "Berberine and Costunolide target two different steps in regulating the EGF signaling, which explains the synergistic anti-cancer effect of DHW." (PMID 32298294, 2020). "Specifically, we observed that upon treatment with cetuximab, CAFs increased their secretion of EGF, which was sufficient to render neighboring cancer cells resistant to cetuximab treatment through sustained mitogen-activated protein kinases (MAPK) signaling." (PMID 32481658, 2020). "In fact, many strategies have been attempted to treat cancer patients especially by blocking EGF/EGFR autocrine loop." (PMID 32385236, 2020).